ARHGAP9 (Rho GTPase activating protein 9)
Description:
GTPase activator for the Rho-type GTPases by converting them to an inactive GDP-bound state. Has a substantial GAP activity toward CDC42 and RAC1 and less toward RHOA. Has a role in regulating adhesion of hematopoietic cells to the extracellular matrix. Binds phosphoinositides, and has the highest affinity for phosphatidylinositol 3,4,5-trisphosphate, followed by phosphatidylinositol 3,4-bisphosphate and phosphatidylinositol 4,5-bisphosphate.
Synonyms: MGC1295; 10C; RGL1
Tractability: Small molecule: a structure with a bound ligand is known. Antibody: its Gene Ontology location is reachable by antibodies, with high confidence; the Human Protein Atlas places it where antibodies can reach. PROTAC: ubiquitination databases record sites on it; its protein half-life has been measured.
Gene: Protein-coding gene on chromosome 12 (57,472,262 to 57,488,824, reverse strand). Ensembl gene ENSG00000123329.
Subcellular location (Human Protein Atlas): Plasma membrane; Cell Junctions
Pathways (Reactome):
Signal Transduction: CDC42 GTPase cycle; RAC1 GTPase cycle; RHOA GTPase cycle
Immune System: Neutrophil degranulation
Gene Ontology:
Molecular function: GTPase activator activity; phosphatidylinositol-3,4,5-trisphosphate binding; protein binding
Biological process: regulation of small GTPase mediated signal transduction; small GTPase-mediated signal transduction; signal transduction
Cellular component: cytoplasm; cytosol; extracellular region; plasma membrane; secretory granule lumen
Genetic constraint (gnomAD): Loss-of-function variants: 77 observed, 90.94 expected, observed/expected ratio (o/e) 0.85, 90% interval 0.7 to 1.02. The upper end of that interval is the gene's LOEUF score, 1.02, which puts it in group 4 of 6, group 1 being the genes least tolerant of losing a copy. Missense variants: 941 observed, 980.63 expected, observed/expected ratio (o/e) 0.96, 90% interval 0.91 to 1.01. Synonymous variants: 382 observed, 401.02 expected, observed/expected ratio (o/e) 0.95, 90% interval 0.88 to 1.04.
Homologues: Orthologues: chimpanzee ARHGAP9 (98% identical), macaque ARHGAP9 (96% identical), rabbit ARHGAP9 (88% identical), pig ARHGAP9 (87% identical), dog ARHGAP9 (86% identical), guinea pig ARHGAP9 (77% identical), mouse Arhgap9 (68% identical), rat Arhgap9 (60% identical), tropical clawed frog arhgap9 (37% identical), Caenorhabditis elegans tag-325 (22% identical), Drosophila melanogaster RhoGAP16F (16% identical). Paralogues in human: ARHGAP12 (32% identical), ARHGAP27 (31% identical), ARHGAP15 (25% identical).
Diseases named in the same sentence as ARHGAP9 in open-access papers:
ARHGAP9 is named in the same sentence as 24 diseases in open-access papers, as found by Europe PMC text mining. Sharing a sentence is not in itself a finding about the gene and the disease. The quoted sentences say what the papers report.
breast carcinoma (5 papers, 2020 to 2024). "Recent results from a bioinformatics analysis of patients with breast cancer and healthy individuals revealed that high levels of ARHGAP9 expression were associated with better prognosis, including preferable relapse-free survival and overall survival." (PMID 32143590, 2020). "Low expression of ARHGAP9 was found in hepatocellular carcinoma and bladder cancer, whereas high expression of ARHGAP9 was observed in breast cancer." (PMID 33579308, 2021). "Besides, it was also reported that ARHGAP9 overexpression resulted in poor survival of breast cancer patients while ARHGAP9 silence inhibited the proliferation, migration and invasion in breast cancer." (PMID 35040754, 2022). "A previous report indicated that ARHGAP9 expression in breast cancer was correlated with poor patient survival, implying that ARHGAP9 could act as an oncogene." (PMID 32143590, 2020). "Their findings revealed that silencing ARHGAP9 inhibited proliferation, migration, invasion and induced cell cycle G0/G1 arrest and apoptosis in breast cancer cells, effects that might be mediated by significant inhibition of ERK and p38 activity." (PMID 32143590, 2020). "They concluded that ARHGAP9 might be a promising target for precision treatment of breast cancer." (PMID 32143590, 2020). "High expression levels of ARHGAP9, 15 and 30, for instance, have been correlated with better RFS and OS in breast cancer." (PMID 39075640, 2024).
hepatocellular carcinoma (4 papers, 2018 to 2021). A malignant tumor that arises from hepatocytes. "In HCC (hepatocellular carcinoma), ARHGAP9 supported MET and E-cadherin upregulation, and inhibited migration." (PMID 34659373, 2021). "ARHGAP9 inhibits the migration and invasion of hepatocellular carcinoma cell by increasing FOXJ2/E-cadherin expression." (PMID 33579308, 2021). "ARHGAP9 also showed a good prognosis in bladder cancer, hepatocellular carcinoma, and gastric cancer." (PMID 33579308, 2021). "Here, we aimed to clarify the expression and functional role of ARHGAP9 in hepatocellular carcinoma (HCC)." (PMID 30206221, 2018).
acute myeloid leukemia (3 papers, 2021 to 2022). Acute myeloid leukemia (AML) is a group of neoplasms arising from precursor cells committed to the myeloid cell-line differentiation. "The study held the opinion that ARHGAP9 gained a huge growth in acute myeloid leukemia patients and ARHGAP9 overexpression is related with the low overall survival rate." (PMID 35040754, 2022). "SOX4-induced ARHGAP9 overexpression also promoted the progression of acute myeloid leukemia." (PMID 35573654, 2022). "However, the exact role of ARHGAP9 in acute myeloid leukemia (AML) has yet to be clarified." (PMID 33579308, 2021).
gastric cancer (3 papers, 2018 to 2021). A primary or metastatic malignant neoplasm involving the stomach. "By contrast, silencing ARHGAP9 reduces the proliferation, migration, and invasion of breast and gastric cancer cells in vitro." (PMID 33579308, 2021).
liver cancer (3 papers, 2022). An epithelial or non-epithelial malignant neoplasm that arises from the liver. "Researchers held the opinion that ARHGAP9 expression had close relation with poor patient survival and its upregulation exhibited suppressive effects on the invasion, proliferation and migration of liver cancer cells." (PMID 35040754, 2022). "Ginsenoside Rg3 significantly inhibits the growth of a variety of liver cancer cell lines, including HepG2, SK-Hep1, MHCC-97L, MHCC-97H, SMMC-7721, and BEL-7404, and effectively inhibits the migration and invasion of liver cancer cells by upregulating ARHGAP9 protein expression." (PMID 35600861, 2022). "Briefly, Rg3 repressed the cancer stemness in both colorectal cancer (LoVo, SW620, HCT116) and liver cancer cells (HepG2, MHCC-97L) via reductions in CD24, CD44, and the epithelial cell adhesion molecule (EpCAM) and activation of ARHGAP9, a tumor suppressor gene." (PMID 36012338, 2022).
lung carcinoma (3 papers, 2022 to 2025). "GATA5 transcriptionally activated ARHGAP9, and restoration of ARHGAP9 expression significantly inhibited proliferation, migration, and invasion of lung-cancer cells, revealing the GATA5-ARHGAP9 axis as a potential therapeutic target." (PMID 41514651, 2025). "The study found that ARHGAP9 upregulation had a significant inhibitory effect on proliferation, invasion and migration of lung cancer cells." (PMID 35040754, 2022). "Based on statistical analysis in the GEPIA database, ARHGAP9 expression was found to be significantly lower in lung cancer tissue than in paired normal tissues." (PMID 35040754, 2022). "Expression of ARHGAP9 in lung cancer was analyzed by GEPIA database." (PMID 35040754, 2022). "ARHGAP9 was downregulated in patients suffering from lung carcinoma." (PMID 35040754, 2022).
bladder cancer (2 papers, 2021 to 2022). "Additionally, ARHGAP9 was supposed to be a useful marker for the treatment of bladder cancer as its downregulated was correlated with bladder prognosis, and the study found a nearly 3-fold increased risk of cancer-specific death when ARHGAP9 levels were reduced." (PMID 35040754, 2022).
coronary artery spasm (1 paper, 2021). "Moreover, the polymorphism of ARHGAP9 is associated with coronary artery spasm." (PMID 34926685, 2021).
endothelial dysfunction (1 paper, 2021). In vascular diseases, endothelial dysfunction is a systemic pathological state of the endothelium (the inner lining of blood vessels) and can be broadly defined as an imbalance between vasodilating and vasoconstricting substances produced by (or acting on) the endothelium. "Among them, ARHGAP9 has been found to lead to endothelial dysfunction in patients with coronary spastic angina." (PMID 34926685, 2021).
lung adenocarcinoma (1 paper, 2022). A carcinoma that arises from the lung and is characterized by the presence of malignant glandular epithelial cells. "Subsequently, we further investigated the role of ARHGAP9 in lung adenocarcinoma by transfecting overexpressed ARHGAP9 plasmids into lung adenocarcinoma cells." (PMID 35040754, 2022). "And the suppressive effects of ARHGAP9 overexpression on proliferation, invasion and migration in lung adenocarcinoma were reversed by GATA5 silencing." (PMID 35040754, 2022). "Results from GEPIA database also showed that ARHGAP9 downregulation was related to the low overall survival rate of lung adenocarcinoma patients." (PMID 35040754, 2022). "According to the GEPIA database analysis, GATA5 and ARHGAP9 were found to be low expressed in lung adenocarcinoma, and they were positively correlated, and in addition ARHGAP9 low expression was associated with poor prognosis in lung adenocarcinoma." (PMID 35040754, 2022). "Whatʹs more, GATA5 silencing reversed the inhibitory effects of ARHGAP9 overexpression on the proliferation, invasion and migration in lung adenocarcinoma cells." (PMID 35040754, 2022). "To conclude, the present study successfully demonstrated for the first time that GATA5-induced ARHGAP9 upregulation has a protective effect on lung adenocarcinoma cells." (PMID 35040754, 2022). "The present study found that ARHGAP9 was low expression in lung adenocarcinoma and had relation with poor prognosis." (PMID 35040754, 2022). "More importantly, GATA5 silencing reversed the inhibitory effect of ARHGAP9 upregulation on the malignant progression of lung adenocarcinoma cells." (PMID 35040754, 2022). "Elsewhere, it was found that the ARHGAP9 expression was significantly correlated with the pathological phase of lung adenocarcinoma." (PMID 35040754, 2022). "In this study, we discovered that GATA5 was downregulated in lung adenocarcinoma tissues and positively correlated with ARHGAP9 in lung adenocarcinoma." (PMID 35040754, 2022). "Notably, the low expression of ARHGAP9 had close relation with the low disease-free survival rate of lung adenocarcinoma patients." (PMID 35040754, 2022). "Moreover, ARHGAP9 upregulation remarkably inhibited lung adenocarcinoma cell proliferation, invasion and migration as compared to the control group." (PMID 35040754, 2022). "Therefore, the present study focused on the effect of promoting GATA5 to induce ARHGAP9 on the malignant process of lung adenocarcinoma cells." (PMID 35040754, 2022). "Notably, regulation of GATA5 was found to directly affect the mRNA and protein expression of ARHGAP9 in lung adenocarcinoma cells." (PMID 35040754, 2022). "The results of the present study were consistent with expectations, when ARHGAP9 was upregulated, lung adenocarcinoma cell proliferation was suppressed significantly in comparison with the control group, while the invasion and migration ability of cancer cells were diminished." (PMID 35040754, 2022). "Besides, it is noted that GATA5 was positively correlated with ARHGAP9 expression in lung adenocarcinoma." (PMID 35040754, 2022). "Thus, the present study was the first to suggest a protective effect of GATA5 induced ARHGAP9 on lung adenocarcinoma cells." (PMID 35040754, 2022). "ARHGAP9 upregulation inhibited the malignant progression of lung adenocarcinoma cells." (PMID 35040754, 2022). "Thus, the study successfully demonstrated that GATA5 could positively induce ARHGAP9 to inhibit lung adenocarcinoma cell progression." (PMID 35040754, 2022).
renal fibrosis (1 paper, 2025). A final common manifestation of a wide variety of chronic kidney diseases characterized by glomerulosclerosis and tubulointerstitial fibrosis. "In summary, we identified five key genes (SFN, ARHGAP9, VSIG4, ISG20, CD3G) that can distinguish patients with renal fibrosis from controls, making them potential biomarkers for disease diagnosis and treatment monitoring." (PMID 41218386, 2025).
tumor (10 papers, 2018 to 2025). "GRg3 effectively inhibited the migration and invasion of HCC cells HepG2 and MHCC-97L and tumor growth in BABL/c nude mice by upregulating the protein expression of ARHGAP9." (PMID 36313365, 2022). "Specifically, ARHGAP9-203 was upregulated in exhausted T cells and tumor-infiltrated Tregs, while ARHGAP9-204 was mainly expressed in naïve T cells and peripheral blood Tregs." (PMID 33674641, 2021). "Using the UALCAN and GEPIA databases, we subsequently tested the mRNA expression of ARHGAP9 in different human tumor samples." (PMID 33579308, 2021). "Our data identify ARHGAP9 as a potential tumor suppressor in HCC." (PMID 30206221, 2018). "We also investigated the molecular mechanism how ARHGAP9 suppressed tumor metastasis." (PMID 30206221, 2018). "Our study provides novel insights into the tumor suppressive role of ARHGAP9 in HCC." (PMID 30206221, 2018). "This inconsistence might be attributed to difference in action mechanisms of ARHGAP9 in various cancers where genetic instability, cellular response and formation of the tumor microenvironment might also differ owing to tissue-derived specificities and heterogeneity." (PMID 32143590, 2020). "The most downregulated genes contained known tumor suppressors (ZNF831, AKNA, NR4A1, ARHGAP9, ZBTB16) and regulators of immune response (NLRC5, WDFY4, RASGRP2, IKZF1)." (PMID 39794830, 2025). "Other RhoGAPs, such as ARHGAP4, ARHGAP6, ARHGAP9, ARHGAP12 and ARHGAP25, have also demonstrated tumor suppressor roles in different types of tumors 26-30." (PMID 36168627, 2022).
cancer (7 papers, 2017 to 2022). A tumor composed of atypical neoplastic, often pleomorphic cells that invade other tissues. "ARHGAP9, also known as RhoGAP9, was testified to be a cancer-associated gene." (PMID 35040754, 2022). "ARHGAP9 has been implicated in regulating adhesion of hematopoietic cells to the extracellular matrix, which is correlated with cell proliferation, migration and invasion in several cancers." (PMID 32143590, 2020). "Rho GTPase activating protein 9 (ARHGAP9) is expressed in various types of cancers and can inactivate Rho GTPases that mainly regulate cytoskeletal dynamics." (PMID 33579308, 2021). "The transcriptional levels of ARHGAP9 in cancers were then compared with those in normal samples by using the GEPIA database." (PMID 33579308, 2021). "Finally, we extracted the top 20 in-degree and top 20 out-degree genes as the hub nodes of each cancer and identified six co-owned immune feature genes (CD48, GPR65, C3AR1, CD2, CD3E and ARHGAP9) in these cancers." (PMID 35069897, 2022). "The mRNA expression levels of ARHGAP9 was the highest among all types of human cancers." (PMID 33579308, 2021). "We found that ARHGAP9 expression was higher in the tissues and cell lines extracted from patients with AML than corresponding control tissues and other cancer types." (PMID 33579308, 2021). "Similarly, NKG7, ARHGAP9, C1QA, and CD53 were accurately predicted in 15/28 datasets (R = 0.38–0.46 for the various cancer types)." (PMID 32747659, 2020).
metabolic disease (1 paper, 2021). A congenital disorder (due to inherited enzyme abnormality) or acquired (due to failure of a metabolically important organ) disorder resulting from an abnormal metabolic process. "Our result suggested that upregulated TTTY15 and ARHGAP9 may play a vital role in metabolic disease, which could be used as PDC biomarkers to assist in clinical diagnosis." (PMID 34926685, 2021).
ARHGAP9 also shares sentences with these, for which no sentence is quoted: colorectal cancer (2 papers); infection (2); acne (1); aortic aneurysm (1); bladder (1); hypothyroidism (1); leukemia (1); non-small cell lung carcinoma (1); Obesity (1); ovarian carcinoma (1).